SHTN1 (shootin 1)
Description:
Involved in the generation of internal asymmetric signals required for neuronal polarization and neurite outgrowth. Mediates netrin-1-induced F-actin-substrate coupling or 'clutch engagement' within the axon growth cone through activation of CDC42, RAC1 and PAK1-dependent signaling pathway, thereby converting the F-actin retrograde flow into traction forces, concomitantly with filopodium extension and axon outgrowth. Plays a role in cytoskeletal organization by regulating the subcellular localization of phosphoinositide 3-kinase (PI3K) activity at the axonal growth cone. Also plays a role in regenerative neurite outgrowth. In the developing cortex, cooperates with KIF20B to promote both the transition from the multipolar to the bipolar stage and the radial migration of cortical neurons from the ventricular zone toward the superficial layer of the neocortex. Involved in the accumulation of phosphatidylinositol 3,4,5-trisphosphate (PIP3) in the growth cone of primary hippocampal neurons.
Synonyms: KIAA1598; shootin1; shootin-1
Tractability: Antibody: the Human Protein Atlas places it where antibodies can reach. PROTAC: ubiquitination databases record sites on it; its protein half-life has been measured.
Gene: Protein-coding gene on chromosome 10 (116,881,477 to 117,126,586, reverse strand). Ensembl gene ENSG00000187164.
Subcellular location: Perikaryon; Cell projection, axon; Cell projection, growth cone; Cytoplasm, cytoskeleton; Cell projection, filopodium; Cell projection, lamellipodium
Subcellular location (Human Protein Atlas): Cytosol; Plasma membrane; Basal body; Centrosome; Nucleoplasm
Pathways (Reactome):
Developmental Biology: Recycling pathway of L1
Gene Ontology:
Molecular function: cadherin binding; protein binding; actin filament binding; kinesin binding
Biological process: positive regulation of neuron migration; actin filament bundle retrograde transport; axonogenesis; Cdc42 protein signal transduction; cytoplasmic actin-based contraction involved in cell motility; endoplasmic reticulum polarization; netrin-activated signaling pathway; neuron projection morphogenesis; positive regulation of axon extension; Ras protein signal transduction; regulation of establishment of cell polarity; substrate-dependent cell migration, cell extension
Cellular component: cytoplasm; microtubule; axon; axonal growth cone; cell leading edge; filopodium; growth cone; lamellipodium; microtubule associated complex; microtubule cytoskeleton; perikaryon; perinuclear region of cytoplasm; cytoskeleton
Genetic constraint (gnomAD): Loss-of-function variants: 16 observed, 39.26 expected, observed/expected ratio (o/e) 0.41, 90% interval 0.28 to 0.62. The upper end of that interval is the gene's LOEUF score, 0.62, which puts it in group 2 of 6, group 1 being the genes least tolerant of losing a copy. Missense variants: 373 observed, 415.58 expected, observed/expected ratio (o/e) 0.9, 90% interval 0.82 to 0.98. Synonymous variants: 131 observed, 142.88 expected, observed/expected ratio (o/e) 0.92, 90% interval 0.8 to 1.06.
Homologues: Orthologues: chimpanzee SHTN1 (95% identical), macaque SHTN1 (94% identical), pig SHTN1 (93% identical), guinea pig SHTN1 (93% identical), dog SHTN1 (91% identical), mouse Shtn1 (91% identical), rat Shtn1 (88% identical), rabbit SHTN1 (88% identical), tropical clawed frog shtn1 (55% identical), zebrafish shtn1 (35% identical), Drosophila melanogaster Frl (16% identical), Caenorhabditis elegans daam-1 (15% identical), and 3 more. Paralogues in human: FMNL2 (19% identical), FMNL1 (18% identical), DIAPH1 (17% identical), DIAPH2 (17% identical), DIAPH3 (17% identical), FMNL3 (17% identical), INF2 (17% identical), DAAM2 (14% identical), FHOD3 (14% identical), DAAM1 (14% identical), FMN2 (13% identical), FHOD1 (13% identical), and 6 more.
Diseases named in the same sentence as SHTN1 in open-access papers:
SHTN1 is named in the same sentence as 9 diseases in open-access papers, as found by Europe PMC text mining. Sharing a sentence is not in itself a finding about the gene and the disease. The quoted sentences say what the papers report.
cholangiocarcinoma (2 papers, 2017 to 2025). A carcinoma that arises from the intrahepatic biliary tree (intrahepatic cholangiocarcinoma) or from the junction, or adjacent to the junction, of the right and left hepatic ducts (hilar cholangiocarcinoma). "Our findings establish FGFR2::SHTN1 as a potent oncogenic driver in various cancers, particularly in cholangiocarcinoma, highlighting a unique mechanism of constitutive activation mediated by Shootin1’s CCD-II domain." (PMID 41496852, 2025).
brain cancer (1 paper, 2021). A primary or metastatic malignant neoplasm affecting the brain. "In primary brain cancers, FGFR1 gain-of-function mutations, kinase domain duplications and fusions, mainly with TACC1, FGFR2 fusions with CTNNA3 or KIAA1598/SHTN1, and FGFR3-TACC3 fusions were reported." (PMID 33853673, 2021).
breast carcinoma (1 paper, 2024). "Our study confirms at several levels that SHTN1 and KIF5B interact with both PRMT5 and RELA in luminal A breast cancer cells." (PMID 38417630, 2024).
cancer (4 papers, 2016 to 2025). A tumor composed of atypical neoplastic, often pleomorphic cells that invade other tissues. "The identification and detailed characterization of the FGFR2::SHTN1 fusion contribute significantly to the growing understanding of oncogenic gene fusions as potent drivers in human cancer." (PMID 41496852, 2025). "From 10,967 patient samples spanning 32 cancer types in the Atlas, our query identified SHTN1 alterations in 154 individuals." (PMID 41496852, 2025). "Our pan-cancer analysis reveals broad dysregulation of SHTN1, with distinct alteration patterns across tumor types." (PMID 41496852, 2025). "FGFR2::SHTN1 fusions were identified via cancer genomics databases and modeled using AlphaFold and HADDOCK." (PMID 41496852, 2025). "These regulatory mechanisms become particularly relevant in the context of the FGFR2::SHTN1 fusion identified in cancers." (PMID 41496852, 2025). "The detailed characterization of the FGFR2::SHTN1 fusion’s genetic and protein architecture, combined with our findings on Shootin1’s intrinsic oligomerization capabilities, allowed us to propose a comprehensive model for its constitutive activation in cancer." (PMID 41496852, 2025). "We retrieved and visualized SHTN1 genomic alteration frequencies from The Cancer Genome Atlas (TCGA) Pan-Cancer Atlas studies using cBioPortal." (PMID 41496852, 2025). "Despite their presence across numerous cancers, it remains unclear whether these SHTN1 alterations represent drivers of tumorigenesis or are merely passenger events; their specific molecular correlates thus require elucidation." (PMID 41496852, 2025).
tumor (2 papers, 2017 to 2025). "Together, these properties suggest that the FGFR2::SHTN1 fusion protein may act as a multifunctional oncoprotein, simultaneously driving transcriptional and cytoskeletal programs that promote tumor progression." (PMID 41496852, 2025).
SHTN1 also shares sentences with these, for which no sentence is quoted: glioblastoma (1 paper); infection (1); low grade glioma (1); neurological disorders (1).